S100A4 (S100 calcium binding protein A4)
Diseases named in the same sentence as S100A4 in open-access papers (continued):
Sharing a sentence is not in itself a finding about the gene and the disease.
colorectal cancer (continued). "Niclosamide represses transcription of S100A4 by inhibiting β-catenin expression and its binding to TCF (T-cell factor) which results in reduced migration of cells and lower metastasis burden in mice with colorectal carcinoma." (PMID 35326507, 2022). "S100A4 knock-down did not change the proliferative capacity of cells which replicates findings in a study on colorectal carcinoma but contrasts some others." (PMID 35326507, 2022). "The present study confirms that nuclear S100A4 expression is a negative prognostic biomarker in colorectal cancer, but the clinical utility in selection of patients for adjuvant fluoropyrimidine‐based chemotherapy is limited." (PMID 27273130, 2016). "We had chosen these metastasis biomarkers for combination, since they address most relevant signaling pathways in colorectal cancer progression and metastasis: MACC1 - a key regulator of the HGF/Met signaling pathway, and S100A4– a transcriptional target gene of the Wnt/β-catenin signaling pathway." (PMID 23166620, 2012). "In conclusion, our present study is the first to show that knockdown of S100A4 using RNA interference could effectively inhibit proliferation, invasion and metastasis in SW620 colorectal cancer cells." (PMID 22200787, 2012). "Although S100A4 expression could not predict the overall survival, colorectal cancer patients with high S100A4 expression displayed poor disease-free survival." (PMID 31581665, 2019). "Therefore, we speculated that other mechanisms, in addition to Wnt/β-catenin and S100A4 inhibition, may involve in the selective anticancer effect of niclosamide against HMGA2-overexpressing colorectal cancer cells." (PMID 31581665, 2019). "However, the functional significance of S100A4 in colorectal cancer is still not clear." (PMID 22200787, 2012). "The impact of the S100A4-RAGE interaction for cell motility and metastasis formation in colorectal cancer has not been elucidated so far." (PMID 24952599, 2014). "When immunoprecipitated protein from a panel of eight primary colorectal carcinoma biopsies was examined by 2D-PAGE, no clear differences compared to the in vitro samples were detected, except for variations attributable to varying amounts of total S100A4." (PMID 18554396, 2008). "However, S100A4 knockdown did not exhibit higher cytotoxicity in DLD-1-HMGA2 cells as niclosamide did, confirming that S100A4 downregulation was not sufficient to selectively kill HMGA2-overexpressing colorectal cancer cells." (PMID 31581665, 2019).
glioma (58 papers, 2014 to 2026). A benign or malignant brain and spinal cord tumor that arises from glial cells (astrocytes, oligodendrocytes, ependymal cells). "S100A4 was previously reported to be highly expressed in regulatory T cells (Tregs) and exhausted T cells in gliomas and was significantly associated with poor prognosis in patients with glioma and glioblastoma." (PMID 40187353, 2025). "Using an experimental mouse glioma model, the authors further demonstrated the critical role of gene expression of a small calcium-binding protein S100A4, which is also considered as a damage-associated molecular pattern (DAMPs) molecule." (PMID 38274827, 2023). "An association between S100A4 expression and tumor aggressiveness has been confirmed for several tumor types, but the exact mechanism of mesenchymal transition in gliomas promoted by S100A4 protein is unclear." (PMID 38275375, 2023). "Supportive of its role in glioma aggressiveness, elevated S100A4 expression was significantly associated with poor prognosis in glioma and GBM patients." (PMID 35140215, 2022). "In the study, a candidate gene, S100A4, expressed on immunosuppressive macrophages and T-cells, was significantly associated with poor prognosis in glioma and GBM patients." (PMID 36425564, 2022). "In glioma, S100A4 expression is affected by DNA methylation, β-linked proteins, and extracellular factors including epidermal growth factor and tumor necrosis factor alpha (TNF-α)." (PMID 34148033, 2021). "Previously, it was shown that tumor-associated neutrophils can release S100A4, which increases tumor proliferation and the transformation to a mesenchymal subtype in gliomas." (PMID 32756015, 2020). "In human malignant brain tumors, S100A4 was positively linked to pathogenesis, progression, and histogenesis of glioma by the regulation of cell proliferation, migration, and invasion." (PMID 29069865, 2017). "The improved survival rate of S100a4−/− glioma-bearing mice was associated with the generation of anti-tumor immunity, accompanied by increased phagocytic activity of CD11b+ glioma-associated myeloid cells and enhanced activity of CD4+ T cells, stimulating T cell proliferation and IFNγ secretion." (PMID 38274827, 2023). "Taken together, our functional analyses of GAMs and TILs from S100a4−/− host gliomas provide compelling evidence that S100a4 functions in glioma-associated immune cells in a cell-autonomous manner to suppress the immune response and promote glioma growth." (PMID 35140215, 2022). "Specifically, the levels of S100A4 expression have been identified as an independent prognostic indicator of glioma patient survival, the worse prognosis being associated with up-regulated S100A4 expression in patients with glioblastoma of the mesenchymal molecular subgroup." (PMID 33281564, 2020). "An integrated analysis of 201,986 human glioma, immune, and other stromal cells confirmed heterogeneity of tumor microenvironment for gliomas and revealed S100A4 as a regulator of immune suppressive T and myeloid cells in glioblastoma." (PMID 40191211, 2025). "In mouse models of glioma, we showed that S100a4 -/- TAMs have enhanced phagocytic activity compared with wild-type TAMs." (PMID 40078995, 2025). "Through single cell RNA-sequencing of tissues from glioma patients, we showed that S100A4 is highly expressed in exhausted, tumor-infiltrating CD8 T cells and T-regs." (PMID 40078995, 2025). "Concurrently, the expression of S100A4 was upregulated, promoting glioma cell proliferation and migration." (PMID 41268299, 2025). "S100A4-/- mice showed increased OS and increased T cell infiltration compared to wild-type hosts when injected with primary glioma cells." (PMID 38339353, 2024). "Single-cell sequencing analysis identified S100A4 as an important immune-suppressing T-cell regulator in glioma." (PMID 39664902, 2024).
glioma (continued). "Neutrophils promote glioma growth via induction of S100A4 expression in glioma cells, and S100A4 deletion increased the efficacy of anti-VEGFA therapy in tumor-bearing mice." (PMID 36594465, 2023). "S100A4 is a new marker and regulatory factor of glioma stem cells and a molecular chain of mesenchymal transition and stemness of GBM." (PMID 36560848, 2023). "Several S100A members have been involved in glioma aggressiveness, such as S100A4, which regulates the epithelial-mesenchymal transition in glioblastoma and whose expression increases with grade." (PMID 37370678, 2023). "In patients receiving anti-VEGF therapy, neutrophils contribute to glioma resistance to anti-VEGF therapy by increasing S100A4 expression and angiogenesis in glioma tissues." (PMID 38130720, 2023). "S100A4 is known to be a biomarker expressed in glioma stem-like cells (GSCs) that induces the tumorigenic activity of neutrophils." (PMID 38130720, 2023). "We reported previously that S100A4 is necessary for glioma stem cell self-renewal and proneural–mesenchymal transition." (PMID 35140215, 2022). "FACS-sorted GFP+CD45+CD3+CD4+ TILs from S100a4+/− or S100a4−/− host gliomas were co-cultured with naïve B6 wild-type splenocytes and secreted IFN-γ in the conditioned media was measured by ELISA." (PMID 35140215, 2022). "A recent preclinical study identified S100a4 in GBM associated T cells and macrophages as a critical factor promoting immunosuppression and glioma growth." (PMID 35454848, 2022). "Nevertheless, S100a4−/− host mice survived significantly longer than B6 mice transplanted with the same glioma cells on the same day, in two independent glioma models." (PMID 35140215, 2022). "This survival benefit was associated with significantly increased CD45+ immune infiltrates, including CD4+ and CD8+ T cells, in S100a4−/− host gliomas." (PMID 35140215, 2022). "Neutrophils promote the mesenchymal transformation of gliomas via increased expression of S100A4 within the gliomas and increase vascularization, which induces resistance to anti-VEGF therapy." (PMID 35860278, 2022). "An earlier study reported that S100a4−/− macrophages were compromised in their ability to migrate to sites of inflammation; however, our flow cytometry analysis showed that macrophage numbers were equivalent between B6 and S100a4−/− host gliomas." (PMID 35140215, 2022). "Recent studies have demonstrated that S100A4 is directly involved in tumor metastasis and such as breast, non-small-cell lung, and glioma 30-33." (PMID 36046652, 2022). "To specifically determine the functional consequence of inhibiting S100a4 in immune cells, we first deleted S100a4 from the host glioma microenvironment and orthotopically transplanted two independent syngeneic glioma tumorsphere cell lines (5459 and 2808)." (PMID 35140215, 2022). "The results presented here establish a critical role for S100a4 expression in GBM associated T cells and macrophages in promoting immunosuppression and glioma growth." (PMID 35140215, 2022). "To fully determine the effect of S100A4 on glioma cells, we knocked down S100A4 in LN229 cells by transfecting specific siRNA." (PMID 35592707, 2022). "This integrated human glioma analysis reveals considerable spatial, molecular, and functional immune cell heterogeneity in human gliomas and nominates S100A4 as an immunotherapy target." (PMID 35140215, 2022). "As a consequence of reprogrammed myeloid and T cells, S100a4−/− glioma-bearing mice live significantly longer than B6 wild-type host mice, validating the potential of S100A4 as an immunotherapy target in GBM." (PMID 35140215, 2022). "Multivariate analysis of S100A4 expression and tumor subtype, gender, recurrence, IDH status, and MGMT status show that S100A4 is an independent prognostic factor (Multivariate Cox regression analysis p-values: all gliomas = 0.0089, GBM only = 0.0019)." (PMID 35140215, 2022).
glioma (continued). "It was established that in vitro, the migration of C6 glioma cells depended on the expression of S100A4, as its silencing inhibited their motility." (PMID 33918416, 2021). "The risk score was positively correlated to the oncogenes S100A4, TWIST1, CDH2, and POSTN, which were critically involved in glioma migration and invasion." (PMID 32733879, 2020). "It has been reported that the expression of S100A4 is highly correlated with the progression of glioma which indicated that S100A4 plays a vital role in the pathogenesis of glioma." (PMID 32228516, 2020). "Selective ablation of the S100A4-expressing cells in genetically engineered mice that form spontaneous gliomas was sufficient to compromise tumor growth." (PMID 33281564, 2020). "It has been recently reported that S100A4 is a novel marker and a critical regulator of glioma stem cells, with the enhanced S100A4 expression contributing to the presentation of a metastatic phenotype." (PMID 30045697, 2018). "The migration patterns of glioma cells are affected by intrinsic S100A4 expression and by that in their surrounding astrocytes." (PMID 29069865, 2017). "With respect to glial tumors, it has been shown that S100A4 is expressed differentially in astrocytic tumors being its levels higher on those tumors with a higher degree of malignancy." (PMID 25738360, 2015). "Recent data show that expression of S100A4 in tumors of the central nervous system is related to the degree of malignancy of the tumor, with a higher expression of S100A4 in high-grade gliomas compared to low-grade gliomas." (PMID 25738360, 2015). "Glioma cells that express S100A4 demonstrate tumor-initiating and sphere-forming capabilities." (PMID 41141394, 2026). "In addition, S100A4 regulates expression of transcription factors that control the proneural-mesenchymal transition in glioma stem cells." (PMID 40078995, 2025). "In addition to exogenous S100A4 signaling, single-cell RNA sequencing (scRNAseq) of tumor infiltrating immune cells in glioma patients showed that S100A4 is highly expressed in MDSCs and immunosuppressive macrophages." (PMID 40078995, 2025). "Using an S100a4-GFP knock-in reporter mouse with syngeneic mouse glioma models, we previously showed that GFP+ glioma infiltrating CD4 T cells from S100a4 -/- mice had reduced ability to inhibit T cell proliferation in vitro compared with their counterparts from S100a4 GFP/+ mice." (PMID 40078995, 2025). "In addition, T cells infiltrating S100a4-/- glioma-bearing mice displayed high proliferation and IFNγ production." (PMID 38339353, 2024). "Moreover, in vitro and in vivo studies have confirmed that expression of the S100A4 protein by neutrophils promotes the progression of gliomas, leading to a transition to a mesenchymal glioblastoma phenotype and an increased proliferation rate." (PMID 38275375, 2023). "Neutrophils which secrete elastase and produce S100A4 around the glioma could aid glioma infiltration and induce the proliferation of GBM-initiating cells." (PMID 37322408, 2023). "Gliomas with high expression level of S100A4 may be more likely to be classified into more higher grade in the next edition of WHO classification." (PMID 36543888, 2022). "Furthermore, although myeloid cell numbers were not significantly altered, T cell:myeloid cell ratios were significantly increased in S100a4−/− host gliomas due to increased T cell infiltration, indicating effective immune reprogramming." (PMID 35140215, 2022). "Similar to previous studies, S100A4, PLAUR, and EMP3 were found to be associated with glioma progression to high grade and were identified as the hub genes that may affect TAF infiltration in glioma." (PMID 35574375, 2022). "Selectively removing S100A4-expressing cells was able to sufficiently block tumor growth both in vitro and in vivo; and meanwhile, S100A4 is also identified as a critical regulator of glioma stem cells self-renewal both in mouse and patient-derived glioma tumorspheres in this research." (PMID 36046652, 2022).
glioma (continued). "Moreover, knockout S100a4−/− glioma-bearing mice lived significantly longer than wild-type host mice, validating the potential of S100A4 as an immunotherapy target in GBM." (PMID 36425564, 2022). "Targeting S100A4 can also sensitize glioma cells to bevacizumab treatment." (PMID 34671362, 2021). "For instance, S100A4 has been reported to promote malignant progression of glioma." (PMID 34148033, 2021). "Centrogranulocytes can promote the progression and growth of glioma through S100A4." (PMID 34148033, 2021). "Moreover, OAT-1746 treatment affects the expression of genes involved in leukocyte chemotaxis (Ccl2, Ccl7, Ccl17) and supporting glioma migration and invasion (Cme1, S100a4 and Mmp14)." (PMID 34504786, 2021). "In glioma stem cells, S100A4-positive cells had tumor-initiating and sphere-forming properties." (PMID 33549040, 2021). "There is considerable evidence of the correlation between S100A4 and glioma." (PMID 34148033, 2021). "Another study has indicated that S100A4 could be a novel marker and regulator of glioma stem cells in human and murine malignant gliomas." (PMID 30045697, 2018). "Therefore, the drug that targets the S100A4 and neutrophils, together with anti-angiogenic therapies, could be a good strategy to slow glioma growth and reduce treatment resistance." (PMID 41268299, 2025). "Therefore, agents targeting neutrophils and S100A4 combined with standard antiangiogenetic therapy may inhibit glioma progression and diminish antiangiogenic therapy resistance." (PMID 37705736, 2023). "Moreover, as the grade of glioma increases, S100A4 expression also increases." (PMID 34148033, 2021). "ELF4 is elevated in high grade gliomas, particularly in glioma and neuronal stem cell markers, including CD44, CD36, CD15, CD70, S100A4, and ALDH1A3." (PMID 38539424, 2024). "Quantitative PCR and immunohistochemical analysis showed that LIF, LOX, MMP9, S100A4, SRPX2, and TIMP1 were expressed at high levels in glioma, whereas SLITI1 and SMOC1 were expressed at low levels, consistent with our previous results." (PMID 36560848, 2023). "In glioma, NET-derived S100A4 mediates resistance to anti-VEGF therapy, whereas inhibition of S100A4 enhances response to treatment." (PMID 36873885, 2023). "The immunofluorescence staining confirmed the expression of S100A4 in immunosuppressive CD163+, CD206+ macrophages, and FOXP3+ T cells in human glioma." (PMID 37731483, 2023). "The expression of S100A4, EMP3, and PLAUR was increased in recurrent gliomas compared with primary gliomas as were the risk scores of recurrent gliomas." (PMID 35574375, 2022). "The same results were observed when wildtype GAMs (CD45+ CD11b+) were isolated from B6 host gliomas and compared to corresponding cells (CD45+ CD11b+ GAMs) from S100a4−/− host gliomas (p = 0.0004)." (PMID 35140215, 2022). "A series of genes such as EN1, S100A4, ANXA1, PDPN, IGFBP2 and CHI3L1 were upregulated in radiotherapy treated glioma patients, while other genes such as PRLHR, SFRP2, BRINP1, TRIM67, LHX5, KCNIP2 and NSG2 were downregulated." (PMID 34852024, 2021). "S100A3, S100A4, S100A8, and S100A9 expression was up-regulated during the progression of glioma grade." (PMID 34148033, 2021). "Survival analysis showed that the expressions of S100A4, FN1, and MMP-2 were negatively correlated to over-survival significantly in GBM and Brain Lower Grade Glioma." (PMID 33004792, 2020). "Therefore, the targeting of S100A4 may be a promising approach to constrain glioma malignancy." (PMID 32429463, 2020). "Other studies evaluate the inhibition of S100A4 protein function with S100A4-specific antibodies, or by blocking its binding to RAGE with antagonistic peptides, shown for glioma and pancreatic cancer." (PMID 24952599, 2014). "S100A4 may facilitate the enhanced recruitment of neutrophils, contributing to VEGF resistance in gliomas." (PMID 40093000, 2025).